CPLX1 (complexin 1)
Description:
Positively regulates a late step in exocytosis of various cytoplasmic vesicles, such as synaptic vesicles and other secretory vesicles. Organizes the SNAREs into a cross-linked zigzag topology that, when interposed between the vesicle and plasma membranes, is incompatible with fusion, thereby preventing SNAREs from releasing neurotransmitters until an action potential arrives at the synapse. Also involved in glucose-induced secretion of insulin by pancreatic beta-cells. Essential for motor behavior.
Synonyms: CPX-I; CPX1; DEE63; EIEE63
Tractability: PROTAC: its protein half-life has been measured.
Gene: Protein-coding gene on chromosome 4 (784,957 to 827,043, reverse strand). Ensembl gene ENSG00000168993.
Subcellular location: Cytoplasm, cytosol; Perikaryon; Presynapse
Subcellular location (Human Protein Atlas): Vesicles
Pathways (Reactome):
Neuronal System: Acetylcholine Neurotransmitter Release Cycle; Dopamine Neurotransmitter Release Cycle; GABA synthesis, release, reuptake and degradation; Glutamate Neurotransmitter Release Cycle; Norepinephrine Neurotransmitter Release Cycle; Serotonin Neurotransmitter Release Cycle
Gene Ontology:
Molecular function: protein binding; SNARE binding
Biological process: chemical synaptic transmission; exocytosis; modulation of chemical synaptic transmission; regulation of exocytosis; regulation of synaptic vesicle fusion to presynaptic active zone membrane; synaptic vesicle exocytosis; insulin secretion; neurotransmitter transport; regulation of exocytic insertion of neurotransmitter receptor to postsynaptic membrane
Cellular component: cytosol; perikaryon; presynapse; SNARE complex; synaptobrevin 2-SNAP-25-syntaxin-3-complexin complex; terminal bouton; calyx of Held; dendrite; glutamatergic synapse; neuronal cell body; postsynapse; protein-containing complex; Schaffer collateral - CA1 synapse; synapse; synaptobrevin 2-SNAP-25-syntaxin-1a-complexin I complex
Genetic constraint (gnomAD): Loss-of-function variants: 6 observed, 15.66 expected, observed/expected ratio (o/e) 0.38, 90% interval 0.21 to 0.76. The upper end of that interval is the gene's LOEUF score, 0.76, which puts it in group 3 of 6, group 1 being the genes least tolerant of losing a copy. Missense variants: 242 observed, 195.5 expected, observed/expected ratio (o/e) 1.24, 90% interval 1.11 to 1.38. Synonymous variants: 91 observed, 76.34 expected, observed/expected ratio (o/e) 1.19, 90% interval 1 to 1.42.
Homologues: Orthologues: chimpanzee CPLX1 (99% identical), macaque CPLX1 (99% identical), guinea pig CPLX1 (97% identical), mouse Cplx1 (97% identical), rat Cplx1 (97% identical), pig CPLX1 (92% identical), tropical clawed frog cplx1 (89% identical), zebrafish CPLX1 (84% identical), zebrafish cplx2a (73% identical), dog CPLX1 (60% identical), Drosophila melanogaster cpx (40% identical), Caenorhabditis elegans cpx-1 (32% identical), and 1 more. Paralogues in human: CPLX2 (84% identical), CPLX4 (34% identical), CPLX3 (32% identical).
Diseases named in the same sentence as CPLX1 in open-access papers:
CPLX1 is named in the same sentence as 43 diseases in open-access papers, as found by Europe PMC text mining. Sharing a sentence is not in itself a finding about the gene and the disease. The quoted sentences say what the papers report.
Ataxia (7 papers, 2008 to 2024). Ataxia refers to impaired coordination of voluntary muscle movement. "In summary, dysgenesis and neurodegeneration are two possible outcomes of Cplx1 deficiency that results in ataxia in Cplx1−/− mice." (PMID 22393426, 2012). "Studies have shown that Cplx1(−/−) mice have profound ataxia that limits their ability to perform co-ordinated motor tasks, and have pronounced deficits in social behaviors." (PMID 32900904, 2020). "We suggest that the ataxia in Cplx1−/− mice is likely to be due to pathological changes in both cerebellum and thalamus." (PMID 22393426, 2012). "In addition, homozygous Cplx1 knockout mice have the earliest known onset of ataxia seen in a mouse model." (PMID 38671141, 2024). "Mice harboring a mutant Cplx1 gene exhibited ataxia and sporadic convulsions." (PMID 33132826, 2020). "Therefore, it seems likely that pathology in these regions contributes to ataxia and possibly other phenotypic abnormalities observed in the Cplx1−/− mouse." (PMID 22393426, 2012). "The dominant phenotype in Cplx1−/− mice is a severe ataxia, which is present by 2 weeks of age." (PMID 22393426, 2012). "Mice mutant for Cplx1 develop severe ataxia and behavioral disorders." (PMID 18671875, 2008). "As granule cell loss has been reported in Cplx1 −/− mice, which exhibit profound ataxia, PGC-1α may play an important role in regulation of Cplx1 and other dependent genes in granule cells." (PMID 25610371, 2014). "Cplx1 knockout mice (Cplx1−/−) have the earliest known onset of ataxia seen in a mouse model, although hitherto no histopathology has been described in these mice." (PMID 22393426, 2012).
schizophrenia (7 papers, 2008 to 2022). A major psychotic disorder characterized by abnormalities in the perception or expression of reality. "For example, the DMR gene USP6NL was a risk locus for Alzheimer’s disease, and the DMR gene CPLX1 was associated with cognitive resilience, nerve system development, and schizophrenia." (PMID 36344488, 2022). "The DMR gene CPLX1 was aberrantly expressed in patients with schizophrenia and was confirmed as the risk gene of schizophrenia." (PMID 36344488, 2022). "The sample size is modest and precludes us from making any definitive statements on the associations of MIR137 and CPLX1 with schizophrenia in Han Chinese." (PMID 29118371, 2017). "Given the modulatory effect of microRNA137 on complexin 119, we hypothesized a gene interaction between the MIR137 and CPLX1 may confer susceptibility to schizophrenia." (PMID 29118371, 2017). "Future targeted deep sequencing may help to undercover fundamental characteristics of pathogenic MIR137 and CPLX1 mutations and any potential association with schizophrenia." (PMID 29118371, 2017). "In this study, we aimed to investigate whether the variants of MIR137 and CPLX1 confer susceptibility to schizophrenia in Han Chinese." (PMID 29118371, 2017). "Therefore, we hypothesized that the potential interaction effect of MIR137 and CPLX1 may influence the genetic risk for schizophrenia." (PMID 29118371, 2017). "Here, we first used a public database to detect whether CPLX1 differentially expressed in brain between patients with schizophrenia and healthy controls." (PMID 29118371, 2017). "In conclusion, our findings do not support MIR137 and CPLX1 conferring susceptibility to schizophrenia in Han Chinese." (PMID 29118371, 2017). "Our findings do not support MIR137 and CPLX1 conferring susceptibility to schizophrenia in Han Chinese." (PMID 29118371, 2017). "Gene interaction analysis showed that MIR137 SNP rs1625579 did not affect schizophrenia susceptibility in interaction with the CPLX1 polymorphic variants." (PMID 29118371, 2017). "For example, miR-153 regulates Snap25, Vamp2, Snca, Trak2, Bsn and Pclo genes at the mRNA level; miR-137 inhibits complexin-1, Nsf and Syt1 in mouse model of schizophrenia; miR-34c targets VAMP-2 and miR-135a binds the complexin-1 and complexin-2 genes in the amygdala." (PMID 32252776, 2020). "In this study, our results did not support the involvement of MIR137 and CPLX1 in the pathophysiology of schizophrenia, at least in Han Chinese population." (PMID 29118371, 2017).
epilepsy (6 papers, 2019 to 2025). A brain disorder characterized by episodes of abnormally increased neuronal discharge resulting in transient episodes of sensory or motor neurological dysfunction, or psychic dysfunction. "Deficits in the subunits of the core complex (synaptobrevin-2, syntaxin-1B and SNAP-25), Munc18-1 and complexin-1 are mainly associated with an overlapping spectrum of developmental delay, intellectual disability, epilepsy, and movement disorders." (PMID 35095745, 2021). "Mutations of CPLX1 have been associated with epilepsy and intellectual disability, and Cplx1 knockout mice exhibit pronounced motor and social deficits." (PMID 31297068, 2019). "Future studies may integrate GFAP scoring with detailed gene-level analyses to better understand how specific genes within the 4p16.3 region—such as NSD2 (associated with developmental delay), LETM1 (epilepsy), or CPLX1 (synaptic function)—modulate individual trajectories." (PMID 40725476, 2025). "Importantly, these CPLX1 variants have also been associated with epileptic seizures and epilepsy." (PMID 39596051, 2024). "While the focus has been on neurodevelopmental delay and epilepsy, other potential symptoms could include motor impairments and cognitive deficits, as synaptic function in CPLX1-related pathways is critical to a wide range of neuronal processes." (PMID 39596051, 2024).
Anxiety (4 papers, 2019 to 2025). Intense feelings of nervousness, tension, or panic often arise in response to interpersonal stresses. "Melatonin has also been reported to it could lessen anxiety and depression‐like behaviors of AD mice by regulating the expression of glutathione S‐transferase P1 (GSTP1) and complexin‐1 (CPLX1) in the hippocampus." (PMID 39056330, 2024).
developmental delay (4 papers, 2019 to 2025). "The CPLX1 variants were involved in patients with ID, developmental delay, and myoclonic epilepsy." (PMID 32900904, 2020). "It has been suggested that C-terminal binding protein 1 (CTBP1), complexin 1 (CPLX1), and phosphatidylinositol glycan anchor biosynthesis class G (PIGG) are possible candidates for developmental delay, intellectual disabilities, and seizures in WHS patients." (PMID 31297068, 2019).
glioma (4 papers, 2017 to 2024). A benign or malignant brain and spinal cord tumor that arises from glial cells (astrocytes, oligodendrocytes, ependymal cells). "Here we show that the CPLX1 gene is suppressed by REST and that higher CPLX1 expression predicts better prognosis in gliomas." (PMID 39602392, 2024).
cognitive decline (3 papers, 2017 to 2025). "A study demonstrating the protection of 12 hippocampal proteins, including CPLX-1 and CPLX-2, reinforces the hypothesis that targeted interventions like CoQ10 may help mitigate the progression of cognitive decline associated with AD." (PMID 40944284, 2025).
intellectual disabilities (3 papers, 2019 to 2023). "This future research would increase our understanding of both the functions of complexin-1 in the CNS function and the complex pathophysiology of intellectual disabilities." (PMID 37066095, 2023). "So far, the functional implications of these variants on neurotransmitter release have not been studied, and how different Cplx1 variants result in a unique epileptic profile accompanied by developmental and intellectual disabilities is a critical question that warrants further investigation." (PMID 37066095, 2023).
Parkinson disease (3 papers, 2017 to 2024). A progressive degenerative disorder of the central nervous system characterized by loss of dopamine producing neurons in the substantia nigra and the presence of Lewy bodies in the substantia nigra and locus coeruleus. "Downregulation of complexin 1 (CPLX1) mRNA was correlated with genotype, but the expression of other Parkinson's disease genes was not." (PMID 28108469, 2017).
alpha-synucleinopathy (2 papers, 2015 to 2017). "Protein levels of SNCA and complexin 1 are increased in midbrain tissue from individuals with idiopathic PD and from mouse models of synucleinopathy." (PMID 28108469, 2017). "Although our experiments were focused on modelling monogenic alpha-synucleinopathy variants of PD (PARK4/1), we are confident that complexin-1 plays a role in the genetically heterogeneous common idiopathic PD." (PMID 25112678, 2015). "Our data from alpha-synucleinopathy mouse models are consistent with a proteome survey of midbrain from sporadic PD patients, which reported significantly elevated levels for complexin-1 and a trend towards elevated levels of 14-3-3 epsilon." (PMID 25112678, 2015). "Complexin-1 may be a better read-out of alpha-synucleinopathy than the previous gold standard 14-3-3." (PMID 25112678, 2015). "A nominally significant inverse correlation was observed for CPLX1 and a trend towards inverse correlation for YWHAE, two phenomena that we had previously identified as synucleinopathy markers in mouse mutant midbrain." (PMID 28108469, 2017).
gastric cancer (2 papers, 2024 to 2025). A primary or metastatic malignant neoplasm involving the stomach. "CPLX1 has been documented to promote malignancy in gastric cancer." (PMID 38797520, 2024).
lung adenocarcinoma (2 papers, 2024 to 2025). A carcinoma that arises from the lung and is characterized by the presence of malignant glandular epithelial cells. "CPLX1 showed raised expression in other types of cancer, including kidney renal clear cell carcinoma, liver hepatocellular carcinoma and lung adenocarcinoma." (PMID 40703507, 2025). "CPLX1 is one of several factors able to influence the activity of cyclin B1 (CCNB1), which is highly expressed in lung adenocarcinoma and associated with poor prognosis." (PMID 38797520, 2024).
neuroblastoma (2 papers, 2017 to 2023). Neuroblastoma (NB) is the most common solid, extracranial childhood tumor. "Despite the small effect size of CPLX1 mRNA downregulation, this observation reproducibly distinguished cohorts of presymptomatic PARK4 heterozygotes in blood, of individuals with RBD in blood, and neuroblastoma cells after SNCA transfection." (PMID 28108469, 2017).
Obesity (2 papers, 2015 to 2022). Accumulation of substantial excess body fat. "This raises the question as to which of the remaining 7/11 genes (LBP, RXRB, CPLX1, GLAK2, CSTL1, SLC9A3, CA12) may also have a role in obesity." (PMID 25651499, 2015).
bipolar disorder (1 paper, 2018). A disorder of the brain that causes unusual shifts in mood, energy, activity levels and the ability to carry out day-to-day tasks. "In addition, genes linked to ID (TCF4, CPLX1, CDK6, KDM5B), ASD (RORA, KDM5B), and bipolar disorder (ZNF804A) were also among the 16 differentially expressed target genes." (PMID 29665782, 2018).
colorectal cancer (1 paper, 2025). A primary or metastatic malignant neoplasm that affects the colon or rectum. "Possible mechanisms underlying the role of CPLX1 in colorectal cancer were analyzed by GSE41258, which revealed that the FERROPTOSIS pathway was significantly enriched and negatively correlated with the CPLX1 expression level." (PMID 40703507, 2025). "Here, our study underscores the pivotal role of CPLX1 as a prognostic biomarker in colorectal cancer, revealing its significant association with immunotherapy resistance and ferroptosis." (PMID 40703507, 2025). "Therefore, we wanted to analyze the mutation of CPLX1 in colorectal cancer." (PMID 40703507, 2025). "Subsequently to validate the effect of CPLX1 on ferrroptosis in colorectal cancer cells at the cellular level, we examined the changes in MDA and Fe2+ content in two types of cells altered with CPLX1." (PMID 40703507, 2025). "CPLX1 was found to be upregulated in colorectal cancer material compared with the normal colon samples." (PMID 40703507, 2025). "This study employs a comprehensive bioinformatics approach to investigate the role of CPLX1 as a novel prognostic biomarker in colorectal cancer (CRC), particularly in relation to immunotherapy resistance and ferroptosis." (PMID 40703507, 2025). "Although we have made some preliminary findings, more in-depth and systematic research work is still needed to more comprehensively understand the specific application value of CPLX1 in colorectal cancer treatment." (PMID 40703507, 2025). "However, the specific molecular mechanism by which CPLX1 promotes colorectal cancer development remains to be clarified by further experimental studies." (PMID 40703507, 2025).
developmental and epileptic encephalopathy (1 paper, 2022). An epilepsy associated with developmental impairment that may be due to either the underlying etiology or the superimposed epileptic activity, or both. "Among these four genes, mutations in the ZNF141 and CPLX1 genes are associated with autosomal recessive postaxial polydactyly type A6 and developmental and epileptic encephalopathy-63, respectively." (PMID 35440058, 2022).
Epileptic encephalopathy (1 paper, 2021). A condition in which epileptiform abnormalities are believed to contribute to the progressive disturbance in cerebral function. "Mutations in complexin-1 (CPLX1) gene lead to epileptic encephalopathy with onset on infancy." (PMID 33959146, 2021).
ischemia (1 paper, 2023). A hypoperfusion of the BLOOD through an organ or tissue caused by a PATHOLOGIC CONSTRICTION or obstruction of its BLOOD VESSELS, or an absence of BLOOD CIRCULATION. "The downregulation of synaptotagmin-1, complexin-1, and neurofilament light polypeptide is likely to reflect degenerative changes following ischemia and is in line with the observed downregulation of the phototransduction cascade." (PMID 37175625, 2023).
lung squamous cell carcinoma (1 paper, 2025). "Reduced levels of CPLX1 were, however, observed in lung squamous cell carcinoma and uterine corpus endometrial carcinoma." (PMID 40703507, 2025).
rapid eye movement sleep behavior disorder (1 paper, 2017). "When analysing individuals with rapid eye movement sleep behavior disorder, the most specific known prodromal stage of general PD, only blood CPLX1 levels were altered." (PMID 28108469, 2017).
type 2 diabetes (1 paper, 2020). "In the discovery cohort, there were 53 differentially methylated regions associated with birthweight, such as loci within Fatty Acid Desaturase 2 (FADS2) and Complexin 1 (CPLX1) genes, which in turn have been associated with type 2 diabetes and glucose-stimulated insulin release, respectively." (PMID 33212948, 2020).
psychiatric disorder (3 papers, 2017 to 2025). A disorder characterized by behavioral and/or psychological abnormalities, often accompanied by physical symptoms. "In the PPI network of these Egr targets in the DG region, the top key nodes tightly associated with distinct psychiatric disorders and addictive behaviors in previous studies included Syt1, Stx1a, Dlg4, Cplx1, Gria1, Snap25, Rab3a, and Bdnf81,86–91." (PMID 37758941, 2023). "Neurodegenerative and psychiatric disorders are correlated with abnormal expression of Cplx1." (PMID 40766759, 2025).